LEP (leptin)
Diseases named in the same sentence as LEP in open-access papers (continued):
Sharing a sentence is not in itself a finding about the gene and the disease.
Obesity (continued). "Appetite-regulating hormones, particularly leptin (hormone stimulating anorexigen hormones) and ghrelin (hormone acting as orexigen), have been the focus of studies aimed at better elucidating the physiopathology of obesity." (PMID 25892993, 2015). "With signaling capacity both peripherally and centrally and release modulated by fat mass, leptin is well positioned to function as a mediator of interactions between the brain and peripheral inflammatory responses, particularly in the context of obesity." (PMID 26217222, 2015). "Alternatively, it is plausible that the leptin resistance that accompanies obesity could mask the effect of leptin in terms of EC tone." (PMID 26447698, 2015). "Our results are consistent with the general consensus that obesity is a contributing factor to increased pancreatic cancer growth and offer a contributing mechanism for enhanced tumor growth mediated by leptin induced changes in STAT3 and/or PI3K-AKT signaling." (PMID 25919692, 2015). "Leptin, a 16 kDa anti-obesity hormone, exhibits various physiological properties." (PMID 25799398, 2015). "We hypothesized that in the presence of genetic or obesity-induced concurrent insulin and leptin resistance, Kiss1 neurons would be unable to maintain reproductive function." (PMID 25946091, 2015). "Therefore, whereas the leptin signaling is uniformly high in obesity, it is possible that the CB2 receptor will better respond to the decreased EC levels when the functional variant Q63 is expressed." (PMID 26447698, 2015). "Additionally, obesity can increase insulin and insulin-like growth factors and obesity-related regulatory proteins, such as leptin and adiponectin." (PMID 26546331, 2015). "Leptin, a 16-kDa adipocyte-derived adipokine, is the product of the obesity (Ob) gene." (PMID 26593914, 2015). "Our results suggest that leptin may act as a risk factor for CVD and might mediate obesity and CVD by augmenting inflammatory events." (PMID 25762868, 2015). "In patients suffering from obesity hypoventilation elevated concentrations of leptin are observed." (PMID 26274965, 2015). "More recent investigations reported that periodontitis was associated with reduced levels of serum adiponectin, and that obesity and periodontitis may regulate the serum levels of leptin in favor of proinflammation." (PMID 26330934, 2015). "The same neuroimaging features could be used to assess the differential impacts of obesity-related hormones such as leptin and ghrelin." (PMID 26536135, 2015). "Furthermore, expression of sOB-R appears to be inverse to adiposity and DHEAS levels, thus contributing to the role of obesity as an accelerator of puberty, and outlining a possible synergic mechanism between adrenarche and leptin for gonadarche induction." (PMID 26697222, 2015). "Chronic leptin administration in male leptin-deficient ob/ob mice down-regulated adipose AQP3 and AQP7 at the same time as it upregulated hepatic AQP9 in parallel with the improvement of obesity and hepatosteatosis observed in this genetically obese animal model." (PMID 26594198, 2015). "Likewise, the well-recognized effects of RYGB in obese humans and rodents demonstrate its ability to overcome the acquired leptin resistance of diet- induced obesity." (PMID 26445459, 2015). "Our findings suggest that, in addition to the central resistance to certain hormones regulating food intake, such as leptin or insulin, central resistance to glucagon-induced hypophagia might also contribute to the development of obesity." (PMID 26909312, 2015). "Importantly, our results support a linkage between obesity and ovarian carcinogenesis, in which leptin can be a key player." (PMID 26053184, 2015). "These basic findings led us to examine whether plasma leptin contributes to the pathophysiology of autonomic dysfunction in obesity in humans." (PMID 26338087, 2015). "We suggest that leptin resistance in obesity deteriorates the bone repair process in INFH." (PMID 25797953, 2015).
Obesity (continued). "The increase in leptin is a result of obesity as adipocytes secrete leptin." (PMID 25797953, 2015). "These assessments have enabled us to further probe the role of gender in the programming of obesity and metabolic dysfunction, by examining the relationships between infant gender and fetal adiposity, insulin resistance and leptin in this large, well-characterised pregnancy cohort." (PMID 26368559, 2015). "There are three important peripheral signals that could participate in the altered GH secretion of obesity, leptin, insulin and ghrelin." (PMID 25782001, 2015). "Remarkably, leptin lies at the interface of lipodystrophy and obesity." (PMID 25859279, 2015). "Interestingly, a short-term NPY overexpression study suggested that NPY influences leptin and insulin secretion independently from food intake and obesity." (PMID 25993471, 2015). "The protective role of obesity in survival among patients with heart failure may be explained by direct antihypertrophic and antiatherogenic effects of leptin in heart." (PMID 26473487, 2015). "ADIPOQ and IL6 variants were not directely related to obesity, leptin resistance or alterations in cardiometabolic markers." (PMID 25897330, 2015). "As the IfitmDel animal does not produce this age-related alteration in expression, there is the intriguing possibility that these increases produce normal compensatory functions towards control of the age-related increases in obesity and altered leptin modulation of metabolic homeostasis." (PMID 25856311, 2015). "In order to determine if tissue source and obesity impacted adipogenic programming, expression of adipocyte (adipsin, leptin, GLUT4), lipolysis (ATGL) and key adipogenesis regulating transcription factor (PPAR-γ) were profiled in ASC at baseline and following 14 days of adipocyte induction." (PMID 26317219, 2015). "Adv36 infection may increase appetite and food intake by decreasing norepinephrine levels and leptin, thereby increasing obesity prevalence." (PMID 26184280, 2015). "This work has highlighted the importance of genes in the leptin pathway (LEP, LEPR, POMC, PCSK1, MC4R) and recently homozygous stop mutations have also been identified in CEP19, encoding the cilia protein CEP19 in a large family with recessive obesity." (PMID 26132294, 2015). "Here we confirm an obesity-induced increase of leptin and improvement of immunity." (PMID 25844479, 2015). "Leptin-mediated sympatho-activation is a well-known mechanism of obesity-induced hypertension." (PMID 26618774, 2015). "The presence of high levels of leptin in obesity certainly makes it a prime candidate for amplifying the risk of NASH progression as both a first and second hit, which not only satisfies the two-hit hypothesis, but also is in line with the multi-hit paradigm." (PMID 25658689, 2015). "Alternatively,” irisin resistance” may be another description for increased levels of irisin in obesity, as has already established for leptin or insulin in obesity." (PMID 27354972, 2015). "Leptin is widely known as an anti-obesity hormone produced and secreted mainly by adipose tissue." (PMID 25799398, 2015). "Others molecules associated with obesity are CRP, adiponectin, and leptin." (PMID 26380303, 2015). "In the current study, there were no changes typically associatedwith obesity in OR rats, since the high-fat diet was not able to promote changes inglucose, lipid, insulin, leptin, or blood pressure profiles." (PMID 26761369, 2015). "Leptin, encoded by the so-called obesity gene, is a 16-kD nonglycosylated protein hormone secreted by adipocytes." (PMID 26368286, 2015). "It is important to highlight that exogenous leptin is efficient in promoting weight loss in obese humans and mice genetic deficient in leptin but not in diet-induced obesity (Blüher, 2014)." (PMID 26578976, 2015).
Obesity (continued). "The extracts can also be tested for their effect on protein–tyrosine phosphatase 1B (PTP1B), a cytosolic enzyme, that not only increase cellular response to insulin, but also elevates leptin signalling and are therefore, a promising strategy for the treatment of diabetes mellitus and obesity." (PMID 25652009, 2015). "In addition to the storage of lipids in the adipose tissue, adipocytokines like adiponectin, leptin, TNF, IL-6, resistin play an important role in tissue physiology and have been shown to be linked to obesity, insulin resistance and β-cell dysfunction." (PMID 28702225, 2015). "Increased leptin and decreased adiponectin from adipose tissue may contribute to the pathogenesis of asthma in obesity." (PMID 26610598, 2015). "How could leptin be responsible for a relatively large proportion of the obesity-induced hypertension?" (PMID 26617526, 2015). "Leptin expression can be induced by obesity, insulin and TNF-α." (PMID 26379553, 2015). "Thus, obesity and pulmonary inflammation were correlated by investigating leptin effects on regulating cPLA2-α expressions." (PMID 26593914, 2015). "Here we report the contribution of obesity and leptin to pancreatic cancer growth utilizing an in vivo orthotopic murine pancreatic cancer model, which resulted in increased tumor proliferation with concomitant increased tumor burden in the diet induced obese mice compared to lean mice." (PMID 25919692, 2015). "Obesity is also closely related to the levels of leptin and adiponectin, adipose specific hormones." (PMID 26694457, 2015). "In particular, high-fat diet emulates responses of the leptin-system defect, including obesity and steatosis, but not as a consequence of a single mutation." (PMID 25973429, 2015). "Leptin was pinpointed as a potential mediator between obesity and cancer." (PMID 26472027, 2015). "Leptin levels are appropriately elevated for degree of obesity, indicating that leptin deficiency is not a cause of the appetite issues." (PMID 28943610, 2015). "Indeed, Lepob/ob mice lacking GluN2B only in AgRP neurons had increased sensitivity towards the anti-obesity actions of recombinant leptin suggesting that GluN2B-NMDARs normally antagonize leptin signaling within hypothalamic AgRP neurons." (PMID 26500840, 2015). "We next determined whether LEP and ADIPOQ DNA methylation levels in adipose tissue and blood were associated with obesity-related complications including dyslipidemia, hyperglycemia and hypertension." (PMID 25929254, 2015). "These interactions may be important in conditions in which leptin and resistin are elevated, such as in obesity." (PMID 26617526, 2015). "Previous reports have found that the adult offspring of IUGR rats displayed hyperphagia, obesity, hypertension, high serum leptin and insulin levels, increased hypothalamic density of leptin and serotonin receptors, and impairment of serotonin and insulin hypothalamic signaling." (PMID 26633942, 2015). "In addition to its well described anti-obesity actions, leptin also has potent beneficial effects on blood glucose balance." (PMID 26500840, 2015). "Since glycerol is a key metabolite for lipid accumulation in fat depots and liver, the improvement of glycerol availability might be involved in the beneficial effects of leptin on obesity and NAFLD." (PMID 26159457, 2015). "Leptin induced motility of tumor cells may therefore be responsible for increased aggressiveness of select pancreatic cancers in the setting of obesity." (PMID 25919692, 2015). "Further studies may be needed to elucidate the role of leptin linking metabolic syndrome, obesity, and GERD." (PMID 26506614, 2015). "Intestinal eosinophil numbers were restored by returning HFD fed mice to normal chow and were unchanged in leptin-deficient (Ob/Ob) mice, indicating that eosinophil depletion is caused specifically by a high fat diet and not obesity per se." (PMID 25837594, 2015).
Obesity (continued). "Our findings are also concordant with fetal metabolic programming studies in humans and rodent models which have lately shown that lower LEP DNA methylation levels in blood, placenta, VAT, liver and muscle are associated with a risk for obesity and metabolic diseases in the offspring." (PMID 25929254, 2015). "These compelling evidences suggested that leptin could be a potential therapeutic target of obesity-related fatty liver disease." (PMID 24838072, 2014). "As leptin acts on every cell in the immune system as well as stromal cells that influence immune cell development, the direct effect of leptin on lymphocyte and macrophage inflammation in obesity remains unclear." (PMID 25157251, 2014). "Therefore, there is a need for further investigation of the epigenetic mechanisms that contribute to leptin expression and resistance in obesity." (PMID 24923522, 2014). "When obesity develops, a decreased sensitivity to leptin occurs in parallel leading to a lesser activity, which may justify the body mass increase and reduced activity." (PMID 25165578, 2014). "In obesity, fat hypertrophy increases the expression and release of the so-called adipocytokines, such as interleukin (IL) 1β, IL-6, resistin, leptin and tumor necrosis factor alpha (TNF-α), that are necessary for cell differentiation and hematopoiesis, among other functions." (PMID 25184806, 2014). "Leptin, a 16 kDa circulating anti-obesity hormone, exhibits many physiological properties." (PMID 25033454, 2014). "Reduction of leptin uptake by the brain of New Zealand Obese mice, a strain that responds to central but not peripheral leptin, suggested that their obesity is at least partly due to deficient leptin transport into the brain." (PMID 25352831, 2014). "Although preceding studies, typically on leptin and growth hormone, have provided important insight into the relationship between obesity and T-cell aging in humans, the effects of obesity indicators and related diseases on human thymic T-cell production need to be examined in a cohort-based study." (PMID 24651652, 2014). "Thus, overnutrition induces hypothalamic ER stress, leading to insulin and leptin resistance and obesity." (PMID 25541737, 2014). "CDCArg + HFD in oppose to HFD decreased blood leptin levels, which could indicate the amelioration of obesity related leptin resistance." (PMID 24750587, 2014). "Treatment with 7i at a dose of 50 mg/kg/day for 35 days reduced the body weight and liver weight of diet-induced obesity mice by 13.5% and 18.4%, respectively, while also improving the serum levels of triglyceride, total cholesterol, leptin, adiponectin, LDL-c, HDL-c." (PMID 24838072, 2014). "Cases of monogenic human obesity have been traced to mutations in LEPTIN, genes in the leptin signaling pathway, and other genes not directly implicated in leptin biology." (PMID 25329148, 2014). "Consequently, treatment of obese people with leptin was given less attention and the focus of obesity research shifted toward the prevention and reversal of the state of leptin resistance." (PMID 25352831, 2014). "Leptin has been strongly associated with a role in the pathophysiology of obesity and metabolic syndrome, although this role has not been well understood or described." (PMID 24885899, 2014). "Previous studies reported that leptin secretion is positively correlated with adiposity, and that TNF-α action is implicated in inflammatory response and insulin resistance, at least in obesity." (PMID 24159189, 2014). "Furthermore, higher leptin levels are indicative of obesity and its risks and delayed latency shows slowed brain speed and attention." (PMID 25251414, 2014). "Because leptin signaling in the brains of these animals was intact, they did not develop obesity or the associated metabolic syndrome." (PMID 25232724, 2014). "According to the analysis, elevated leptin levels increased by 30 times the risk of obesity in men, regardless of the presence of DM, and 17.7 times in women." (PMID 24981337, 2014).
Obesity (continued). "In the older group, BMI correlated with adiponectin and with leptin, but not with chemerin.Adiponectin and leptin levels in elderly T2DM patients seem to be closely linked to obesity and to length of the disease." (PMID 25105135, 2014). "Adiponectin and leptin are known anti-obesity and anti-diabetic adipokines." (PMID 25013896, 2014). "High release of Leptin by adipocytes is reported in obesity, which further induces TSH." (PMID 25258706, 2014). "Both leptin and adiponectin are well-known markers of human obesity." (PMID 25086605, 2014). "The positive association between plasma leptin levels and FMD in patients with diabetes is contrary to previous studies that show an association between hyperleptinemia and impaired endothelial function in patients with obesity and/or MetS." (PMID 24410779, 2014). "Besides its central role in obesity, leptin also increases insulin resistance, which is involved in the pathogenesis of both metabolic syndrome and ischemic heart disease." (PMID 24616817, 2014). "Pathological damage of Leydig cells, oxidative stress in testis tissue, and high leptin level may provide some evidence to clarify the mechanisms of male SH in obesity and possibly prevent it." (PMID 24829619, 2014). "Herein we examined the mechanism of the EDHF-dependent vasodilatory effect of leptin and tested the hypothesis that alterations of acute vascular effects of leptin in obesity are accounted for by chronic hyperleptinemia." (PMID 24475175, 2014). "According to the multivariate logistic regression analysis, elevated leptin levels increased by 30 times the risk of obesity in men, regardless of the presence of type 2 diabetes, and 17.7 times in women." (PMID 24981337, 2014). "It has been hypothesized that dysregulated production of adipocytokines (PAI-1, leptin, resistin, visfatin, adiponectin) and cytokines (TNF-α and IL-6) from accumulated fat participates in the pathogenesis of obesity-associated MS." (PMID 25548896, 2014). "The retroperitoneal fat pad was chosen because it is one of the major sites of leptin production in rodents, and it may be related to the metabolic complications of obesity." (PMID 24243000, 2014). "Our results indicate that 400 and 200 mg/kg fGT extract had enhanced anti-obesity effects on db/db mice (decreased adipose tissue accumulation and adipocyte hypertrophy, decreased serum leptin levels, and increased serum and periovarian fat adiponectin contents) compared with GT extract." (PMID 25207824, 2014). "Thus, the effect of leptin on breast cancer growth warrants further investigation since leptin is considered to be one of the main mediators in the obesity-breast cancer connection." (PMID 24959279, 2014). "Given the lack of effect on body weight after 4.5 months on a high fructose diet, the duration of a high-fructose diet may need to be considerably longer to induce obesity or leptin resistance." (PMID 25211467, 2014). "In the introduction to their 1994 Nature report describing the identification of leptin, Zhang and colleagues wrote: “Obesity is the commonest nutritional disorder in Western societies” and “The molecular pathogenesis of obesity is unknown”." (PMID 25177314, 2014). "As such, it could be argued that the inhibitory action of fat mass (and associated adiposity signals) on food intake is actually weaker at higher levels of fat mass, and this asymmetry may reflect increased “leptin resistance” with obesity." (PMID 24734042, 2014). "In leptin-deficeint (Lepob/ob) and leptin-receptor-deficient (LepRdb/db) mice, the development of obesity increases HDL without an increase in VLDL, which has been shown to make these animals resistant to the development of atherosclerotic lesions." (PMID 24672716, 2014). "Although this result is at variance with previous studies, the “hypophagia” observed with obesity may be due to the high serum leptin level." (PMID 24466104, 2014).